UPF1 (UPF1 RNA helicase and ATPase)
Diseases named in the same sentence as UPF1 in open-access papers (continued):
Sharing a sentence is not in itself a finding about the gene and the disease.
ZIKV infection (continued). "Here we show that nuclear mRNA export is a UPF1 function that is disrupted during ZIKV infection." (PMID 36603024, 2023). "To determine whether ZIKV infection broadly affects NMD, we utilized two publicly available RNA sequencing (RNA-Seq) data sets to compare genome-wide transcriptional alterations found during ZIKV infection to those found following UPF1 knockdown." (PMID 30401782, 2018). "The depletion of UPF1 in NPCs prior to infection resulted in a significant increase in both ZIKV RNA levels and infectious virus production (respectively), indicating that expression of UPF1 restricts ZIKV infection at or before the RNA replication stage." (PMID 30401782, 2018). "In this study, the accumulation of mRNAs in the nucleus induced by ZIKV infection could be recapitulated both by ZIKV capsid expression, which is known to degrade nuclear UPF1, and by UPF1 knockdown, implicating UPF1 and possibly its nuclear localization in this function." (PMID 36603024, 2023). "Similarly, direct involvement of the NMD pathway in flavivirus is corroborated by the identification of the regulator of nonsense transcripts 1 (UPF1) among the ZIKV capsid interactors and the upregulation of several NMD substrate mRNAs upon ZIKV infection both in Huh7 and hNPC." (PMID 31546825, 2019).
pancreatic cancer (4 papers, 2018 to 2025). "(H) Representative IHC image of a pancreatic tumor resulting from orthotopic injection of Upf1-targeted KPC cells for the squamous marker p40 (ΔNp63)." (PMID 33404013, 2021). "(G) Representative H and E image of a pancreatic tumor resulting from orthotopic injection of Upf1-targeted KPC cells." (PMID 33404013, 2021). "LeuAAG-001-N-3p-68-85, which targets UPF1 in pancreatic cancer, was shown in the original study to be significantly upregulated in pancreatic cancer cell lines (BxPC-3 and PANC-1) relative to normal pancreatic duct epithelial cells (HPDE6c7), with relative abundance levels exceeding 3.5-fold." (PMID 40981380, 2025). "(B) Top, experimental strategy for testing whether mimicking UPF1 mis-splicing by deleting exons 10 and 11 promoted pancreatic cancer growth." (PMID 33404013, 2021). "We concluded that inducing the reported Upf1 exon skipping in vivo had no detectable effects on pancreatic cancer growth or acquisition of adenosquamous features in the KPC model." (PMID 33404013, 2021).
colon cancer (3 papers, 2018 to 2025). "Recent studies indicated that UPF1 knockdown could inhibit the proliferation of colon cancer cells through the NMD mechanism." (PMID 33006314, 2020). "Expression of NMD component UPF1 negatively correlates with 3UI-splicing in normal, but not colon cancer, samples." (PMID 40716781, 2025).
diabetes (3 papers, 2018 to 2025). "Specifically, using a broader UPF definition (i.e., defined by UPF1), the association between depression and diabetes was observed only among individuals with high UPF intake." (PMID 40806039, 2025). "The interaction terms under models with both UPF definitions were significantly and positively associated with the likelihood of having diabetes (OR: 1.379, 95% CI: 1.009 to 1.885 for UPF1, and OR: 2.900, 95% CI: 1.197 to 7.028 for UPF2)." (PMID 40806039, 2025). "Likewise, the genomic region within UPF1 gene, covering the top-ranked CpG site is associated with CTCF, Egr1, and two more transcription factors: MYC—involved in the pathogenesis of diabetes, and PU1—initiating insulin resistance as well as regulating lipolysis." (PMID 30545422, 2018).
liver cancer (3 papers, 2016 to 2024). An epithelial or non-epithelial malignant neoplasm that arises from the liver. "Aberrant expression of UPF1 was closely correlated with Edmondson-Steiner grade (P = 0.015), Barcelona Clinic Liver Cancer stage (BCLC; P = 0.020) and portal vein tumor thrombus (PVTT; P = 0.031)." (PMID 26759305, 2016). "To discover new treatments for liver cancer, we addressed the function of UPF1 in HCC." (PMID 35453543, 2022). "Our studies revealed that the growth of liver cancer can be slowed by UPF1 variant overexpression, but not through UPF1-mediated NMD." (PMID 35453543, 2022).
nasopharyngeal carcinoma (3 papers, 2023 to 2026). A carcinoma arising from the nasopharyngeal epithelium. "However, the expression level and function of UPF1 in nasopharyngeal carcinoma (NPC) have remained undocumented until now." (PMID 41293174, 2025).
acute myeloid leukemia (2 papers, 2020 to 2024). Acute myeloid leukemia (AML) is a group of neoplasms arising from precursor cells committed to the myeloid cell-line differentiation. "Interestingly, variants of DHX34 unable to facilitate UPF1 phosphorylation have been found as pathogenic versions specific to inherited forms of acute myeloid leukemia (AML) and myelodysplastic syndrome (MDS)." (PMID 33205750, 2020).
adenosquamous carcinoma (2 papers, 2021 to 2025). A carcinoma composed of malignant glandular cells and malignant squamous cells. "Adenosquamous carcinoma, a rare and aggressive variant of PDAC, commonly harbors somatic mutations in UPF1, a gene involved in nonsense-mediated mRNA decay (NMD)—a cellular mechanism that eliminates mRNAs with premature stop codons." (PMID 41228342, 2025).
embryonal carcinoma (2 papers, 2023 to 2024). A non-seminomatous malignant germ cell tumor characterized by the presence of large germ cells with abundant cytoplasm resembling epithelial cells, geographic necrosis, high mitotic activity, and pseudoglandular and pseudopapillary structures formation. "Likewise, in mouse embryonal carcinoma and human embryonic stem cells, the loss of UPF1 significantly decreased stem cell markers and inhibited proliferation." (PMID 37349371, 2023). "Strong signals in embryonic carcinoma cells (PA-1) and hPSCs were observed only in the presence of both anti-UPF1 and anti-LIN28A antibodies, suggesting that UPF1 and LIN28A directly interact within the cells." (PMID 38167913, 2024).
facioscapulohumeral muscular dystrophy (2 papers, 2016 to 2020). An autosomal dominant disorder affecting the skeletal muscles of the face, scapula, and upper arm. "In another example, overexpression of the double homeobox transcription factor DUX4, observed muscular dystrophy, facioscapulohumeral muscular dystrophy (FSHD), leads to activation of UPF1 proteolytic degradation and, therefore, NMD inhibition." (PMID 32213869, 2020).
fragile X syndrome (2 papers, 2023). A genetic syndrome caused by mutations in the FMR1 gene which is responsible for the expression of the fragile X mental retardation 1 protein. "FMRP deficiency increases UPF1 phosphorylation levels and leads to hyper-activated NMD in cells from fragile X syndrome (FXS) patients." (PMID 36979701, 2023).
HTLV infection (2 papers, 2018 to 2025). "In the context of HTLV infection, the direct correlation between intracellular redistribution of UPF1/CRM1 and NMD inhibition is made difficult because both C8166 and C91PL cells express the viral protein Tax, another NMD inhibitor that we characterised in the past." (PMID 40396490, 2025).
microcephaly (2 papers, 2018 to 2022). A congenital or acquired developmental disorder in which the circumference of the head is smaller than normal for the person's age and sex. "Notably, genetic conditions causing elevated SMG-2/UPF1 phosphorylation have recently been linked to severe developmental retardation, microcephaly and variable facial and organ malformations, emphasizing the health risks associated with deregulated SMG-1 activity." (PMID 35670662, 2022). "However, mice haploinsufficient for NMD factors upstream of UPF1, including Magoh, Rbm8a, and Eif4a3, develop microcephaly (20, –, 22)." (PMID 30401782, 2018). "While knockout of Upf1 and other NMD factors is embryonic lethal in mice, mice haploinsufficient for the EJC components Magoh, Rbm8a, and Eif4a3 exhibit aberrant neurogenesis and microcephaly (20, –, 22)." (PMID 30401782, 2018).
ovarian carcinoma (2 papers, 2019 to 2022). A malignant neoplasm originating from the surface ovarian epithelium. "An examination of the mutational landscape of UPF1 in cBioPortal reveals a broad spectrum of mutations occurring in this protein in a range of cancer types; the highest frequency is observed in endometrial and ovarian cancers." (PMID 31718065, 2019). "Thus, this ovarian cancer type might be an attractive target for UPF1 drug leads, under conditions in which patients have an UPF1 or UPF2 amplification that stimulates the UPF1-dependent NMD pathway." (PMID 31718065, 2019).
prostate carcinoma (2 papers, 2014 to 2020). A carcinoma that arises from epithelial cells of the prostate gland. "which implied that RBP FUS and UPF1 with lncRNA RP11-423H2.3 or LAMTOR5-AS1 interactions might affect prostate cancer progression." (PMID 32117463, 2020).
type 2 diabetes (2 papers, 2024 to 2025). "GAS5 levels are markedly lower in serum samples from individuals diagnosed with type 2 diabetes mellitus (T2DM) and it affects insulin signaling and glucose uptake by binding to UPF1 and regulating insulin receptor expression." (PMID 40563948, 2025). "This agent binds lncRNA GAS5 with high affinity in adipose-derived stem cells, hinders its interaction with UPF1, and prevents lncRNA GAS5 degradation, thereby alleviating type 2 diabetes." (PMID 40563948, 2025).
acute monocytic leukemia (1 paper, 2016). Acute monoblastic leukemia (AML-M5), is one of the most common subtypes of acute myeloid leukemia (AML) that is either comprised of more than 80% of monoblasts (AML-M5a) or 30-80% monoblasts with (pro)monocytic differentiation (AML-M5b). "Indeed, our previous data showed that down-regulation of GMD factors UPF1, PNRC2, or GR promotes the chemotaxis of human acute monocytic leukemia cell lines (THP-1 cells) by up-regulating CCL2 mRNA and CCL2 protein." (PMID 27798850, 2016).
Alzheimer disease (1 paper, 2024). A progressive, neurodegenerative disease characterized by loss of function and death of nerve cells in several areas of the brain leading to loss of cognitive function such as memory and language. "UPF1 has been identified as a RBP binding to circRPPH1 influencing tumor process, and recruited by circLPAR1 to modulating GDF-15 mRNA stability involved in Alzheimer’s disease." (PMID 39300342, 2024).
Burkitt lymphoma (1 paper, 2021). A rare form of malignant mature B-cell non-Hodgkin lymphoma. "In EBV+ AGS-EBV, Burkitt lymphoma AKBM and P3HR-1, as well as LCL cells, we observed a striking enrichment of BRLF1 transcripts with UPF1 relative to the IgG control IP." (PMID 33596193, 2021). "Next, we asked whether robust reactivation of EBV upon UPF1 silencing was also observed in other relevant cell types, such as the human Akata EBV+ Burkitt lymphoma AKBM cells." (PMID 33596193, 2021).
cyst (1 paper, 2008). A sac-like closed membranous structure that may be empty or contain fluid or amorphous material. "Because of the reverse correlation between the levels of the cwp1/2 and upf1 mRNAs we further investigated the effect of giardial UPF1 on cyst formation." (PMID 18974834, 2008). "We also found that overexpression of UPF1 reduced the levels of CWP1 and cyst formation and reduced the mRNA levels and stability of the cwp1, cwp2, cwp3, and myb2 genes." (PMID 18974834, 2008). "We found that overexpression of UPF1 resulted in a significant decrease of the levels of CWP1 and cyst formation and of the endogenous cwp1-3, and myb2 mRNA levels and stability." (PMID 18974834, 2008). "The results suggest that UPF1 may function in reducing the level of CWP1 and cyst formation." (PMID 18974834, 2008).
cystic fibrosis (1 paper, 2018). Autosomal recessive disorder caused by pathogenic variants in the CFTR gene (cystic fibrosis transmembrane conductance regulator), which encodes a chloride and bicarbonate channel expressed in epithelial cells, and follow the diagnosis criteria. "Particularly, when some key factors in NMD pathway are inhibited, such as ATP dependent RNA helicase upframeshift 1 (UPF1) and upframeshift 2 (UPF2), a better function of the gene implicated in the pathology of cystic fibrosis was noticed." (PMID 30761300, 2018).
epilepsy (1 paper, 2023). A brain disorder characterized by episodes of abnormally increased neuronal discharge resulting in transient episodes of sensory or motor neurological dysfunction, or psychic dysfunction. "As miR-128, which targets the NMD system, including UPF1, is decreased in human epilepsy, it can be the cause of increased UPF1 levels." (PMID 36766761, 2023).
head and neck squamous cell carcinoma (1 paper, 2025). A squamous cell carcinoma that arises from any of the following anatomic sites: lip and oral cavity, nasal cavity, paranasal sinuses, pharynx, larynx, and salivary glands. "To further validate the pathways associated with UPF1 in cancer, we utilized expression data from head and neck squamous cell carcinoma (HNSC) available in TCGA to conduct Pathway activity analysis based on MSigDB Hallmark gene sets." (PMID 41293174, 2025).
neuroblastoma (1 paper, 2024). Neuroblastoma (NB) is the most common solid, extracranial childhood tumor. "We analyzed the 1027 high-confidence NMD targets that we had defined for mouse N2A neuroblastoma cells and shown to be directly or indirectly bound by p-UPF1 using RIP-seq, i.e., anti-p-UPF1 IP of cell lysates followed by RNA sequencing." (PMID 38263082, 2024).
osteoporosis (1 paper, 2020). A condition of reduced bone mass, with decreased cortical thickness and a decrease in the number and size of the trabeculae of cancellous bone (but normal chemical composition), resulting in increased fracture incidence. "In conclusion, GAS5 promotes osteoblast differentiation by targeting the UPF1/SMAD7 axis and protects against osteoporosis." (PMID 33006314, 2020).
osteosarcoma (1 paper, 2017). A usually aggressive malignant bone-forming mesenchymal neoplasm, predominantly affecting adolescents and young adults. "Thus, we utilized the human osteosarcoma U2OS cells as they provided the best knockdown efficiency, with two independent UPF1-specific siRNAs and showed that UPF1 was markedly reduced by both siRNAs." (PMID 29235495, 2017).
ovarian cystadenocarcinoma (1 paper, 2019). An adenocarcinoma that arises from the ovary and is characterized by the presence of cystic structures. "As an example, ovarian cystadenocarcinoma, the missense mutation rate was relatively low, but a relatively high rate of gene amplification was observed, suggesting that the UPF1 activity might be amplified in this particular cancer type." (PMID 31718065, 2019).
pancreatic ductal adenocarcinoma (1 paper, 2021). An infiltrating adenocarcinoma that arises from the epithelial cells of the pancreas. "Tumors derived from control as well as Upf1-targeted cells displayed similar histopathological features characteristic of moderately to poorly differentiated pancreatic ductal adenocarcinomas." (PMID 33404013, 2021). "(F) Representative H and E image illustrating a moderately to poorly differentiated pancreatic ductal adenocarcinoma resulting from orthotopic injection of Upf1-targeted KPC cells." (PMID 33404013, 2021).
pancreatitis (1 paper, 2025). Inflammation of the pancreas. "Five key factors were identified: Wdr1, Naa10p, Ptpn12, Upf1, and Ralb, all significantly upregulated in pancreatitis mice." (PMID 40557397, 2025).
primary effusion lymphoma (1 paper, 2021). A large B-cell lymphoma located in the body cavities, characterized by pleural, peritoneal, and pericardial fluid lymphomatous effusions and that is always associated with human herpes virus-8 (HHV-8). "Similarly, we assessed the enrichment of KSHV transcripts with UPF1 in KSHV+ primary effusion lymphoma (PEL) BCBL1 and HEK293T.rKSHV219 cells." (PMID 33596193, 2021).
recessive dystrophic epidermolysis bullosa (1 paper, 2018). "On the contrary, in recessive dystrophic epidermolysis bullosa, it has been shown that a better response to readthrough was associated with an increase in the factor UPF1 in all cells treated, results which support that the more stable this UPF1 factor is, the more inhibited NMD pathway is." (PMID 30761300, 2018).
rectal cancer (1 paper, 2023). A primary or metastatic malignant neoplasm that affects the rectum. "Moreover, UPF1 expression is elevated in rectal cancer and maintains rectal cancer stem cell stemness." (PMID 36869031, 2023).
renal carcinoma (1 paper, 2022). A carcinoma arising from the epithelium of the renal parenchyma or the renal pelvis. "A series of functional experiments were performed to assess the roles of UPF1 in renal cancer cells." (PMID 36421841, 2022). "Further, cellular experiments proved that knockdown of UPF1 enhanced the invasion, migration, and proliferation abilities in renal cancer cell lines." (PMID 36421841, 2022). "In summary, our results showed that UPF1 might inhibit the proliferation, migration and invasion abilities of renal cancer cells." (PMID 36421841, 2022). "This might explain the low expression of UPF1 in renal cancer, which has feature enhanced oxidative stress." (PMID 36421841, 2022). "Notably, the relationship between UPF1 and renal cancer has not been discussed so far." (PMID 36421841, 2022).
renal cell carcinoma (1 paper, 2024). "Mao found that lncRNA-SLERCC (SLERCC) was lowly expressed in renal cell carcinoma, and further exploration revealed that SLERCC interacted directly with UPF1 and inhibited renal cell carcinoma development through the WNT/β-catenin signaling pathway." (PMID 39253139, 2024).
Renal Clear Cell Carcinoma (1 paper, 2022). "However, the expression profile of UPF1 and its clinical significance in clear cell renal cell carcinoma (ccRCC) remains unclear." (PMID 36421841, 2022).
Sepsis (1 paper, 2024). Sepsis is defined as life-threatening organ dysfunction caused by a dysregulated host response to infection. "Our study demonstrated that UPF1 serves as a RBP of circMAPK1 to promote KDM2B mRNA decay in sepsis-induced lung injury." (PMID 39300342, 2024). "Our findings illustrated a decrease in KDM2B expression in patients with sepsis, and circMAPK1-recruited UPF1 modulating its mRNA stability." (PMID 39300342, 2024). "However, the role of UPF1 in sepsis or macrophage pyroptosis remains undefined." (PMID 39300342, 2024). "Although UPF1 has not yet been explored in sepsis, previous studies have described the association of UPF1 with inflammatory responses in lung ischemia/reperfusion injury, raising the possibility that UPF1 may regulate inflammation in sepsis-induced lung injury." (PMID 39300342, 2024). "Our research adds to this understanding, showing that circMAPK1 was upregulated in sepsis patients and exacerbates lung injury, primarily regulated NLRP3-mediated macrophage pyroptosis via UPF1/KDM2B/WNK1/NLRP3 pathway." (PMID 39300342, 2024). "In conclusion, our findings illustrated that circMAPK1 promoted KDM2B mRNA decay via recruiting UPF1, thereby inhibiting KDM2B-mediated WNK1 demethylation to suppress WNK1 expression, and ultimately triggering NLRP3-mediated pyroptosis to exacerbate sepsis-induced lung injury." (PMID 39300342, 2024). "In summary, we hypothesized that circMAPK1 facilitated KDM2B mRNA decay via recruiting UPF1, and the inhibition of KDM2B-mediated WNK1 demethylation further suppressed WNK1 expression, thus triggering NLRP3-mediated pyroptosis in sepsis-induced ALI." (PMID 39300342, 2024).